PDE10A (phosphodiesterase 10A)
Diseases named in the same sentence as PDE10A in open-access papers (continued):
Sharing a sentence is not in itself a finding about the gene and the disease.
schizophrenia (continued). "In this study, no significant changes in the availability of PDE10A were found in the caudate, putamen, and globus pallidus in patients with schizophrenia compared to controls (% change in patients, −1–6%)." (PMID 35631409, 2022). "This study demonstrated that patients with schizophrenia had normal PDE10A availability in the thalamus, which is consistent with the results of previous preclinical studies showing no change in PDE10A availability in animal models of schizophrenia." (PMID 35631409, 2022). "As this review was in preparation, H. Lundbeck A/S announced halting a trial based on an interim futility analysis of the effects of their PDE10A inhibitor Lu AF11167 against persistent prominent negative symptoms in patients with schizophrenia (BNSS)." (PMID 33551724, 2020). "Disappointingly, PDE10A inhibitors from 3 companies failed to evidence antipsychotic activity in patients with schizophrenia to the same extent as standard-of-care D2 antagonists." (PMID 33551724, 2020). "Intuitively, the finding of reduced striatal PDE10A in patients with schizophrenia would not predict a therapeutic effect of PDE10A inhibitors." (PMID 31119377, 2020). "To date, PDE10A inhibitors have not shown clinical efficacy in the treatment of schizophrenia, and the predictability of this translational model of schizophrenia has not been definitively established." (PMID 31773211, 2020). "In addition, recent findings suggest that phosphodiesterase 10A (PDE10A) also plays a role in neurodegenerative diseases such as Parkinson’s, Huntington’s disease, and schizophrenia." (PMID 29290010, 2017). "For we believe the first time, we show that patients with schizophrenia treated with diazepines have a significantly lower BPND of [11C]Lu AE92686 in the striatum compared to healthy control subjects, indicating a lower availability of PDE10A." (PMID 28267149, 2017). "However, the Pfizer or Takeda PDE10A inhibitors did not produce clinically meaningful improvements in positive symptoms in patients suffering schizophrenia as measured using the PANSS scale, the primary outcome measures in these studies." (PMID 33551724, 2020). "Recently, it has been hypothesized that inhibition of dopaminergic signaling through PDE10A could represent a novel non-receptor-based mechanism for the reduction of psychosis and related cognitive dysfunction in schizophrenia." (PMID 26808689, 2016). "Thus, although PDE10A inhibitors will not be a treatment for schizophrenia, they may still be useful clinical tools in understanding the disorder and in the development of new biomarkers of efficacy and medications." (PMID 33551724, 2020).
Huntington disease (30 papers, 2010 to 2025). Huntington disease (HD) is a rare neurodegenerative disorder of the central nervous system characterized by unwanted choreatic movements, behavioral and psychiatric disturbances and dementia. "Inhibition of PDE10A reduced striatal and cortical cell loss, the degree of microglial activation, and deficits in rotarod performance in a mouse model of Huntington’s disease." (PMID 28753652, 2017). "Although human mutations in the PDE10A gene manifest in hyperkinetic movement disorders that phenocopy many features of early Huntington’s disease, characterization of the maladapted molecular mechanisms and aberrant signaling processes that underpin these conditions remains scarce." (PMID 31871190, 2020). "It is noteworthy that early in Huntington disease progression there is a decline in PDE10A expression levels in the striatum, as determined in post-mortem studies as well as with PDE10A PET imaging." (PMID 39056811, 2024). "As Huntington’s disease is associated with a reduced transcription of cyclic AMP early in the disease, we observed a downregulation in the expression of PDE10A and PDE1B, two cAMP/cGMP phosphodiesterases highly expressed in MSNs." (PMID 36523271, 2022). "PDE10A inhibitors are being developed for psychiatric disease and are considered possible therapeutics in Huntington’s disease." (PMID 32378029, 2021). "On the other hand, elevating cyclic nucleotides in symptomatic Huntington’s chorea animal models using PDE10A inhibitors restored basal ganglia function, despite a dramatic loss of the PDE10A enzyme." (PMID 31119377, 2020). "Phosphodiesterase 10A (PDE10A) is as a target of interest in Huntington’s disease (HD) as levels of the enzyme have been shown to decrease prior to the development of the hallmark motor symptoms." (PMID 31871190, 2020). "In other neurological disorders including Huntington’s disease (HD) and schizophrenia, PDE10A has long been considered a promising target for pharmacological treatment." (PMID 29948482, 2018). "The positron emission tomography (PET) tracer [18F]MNI-659, selective for phosphodiesterase 10A (PDE10A), is a promising tool to assess an early biomarker for Huntington’s disease (HD)." (PMID 30365550, 2018). "It has been also reported that PDE10A inhibition improves cortico-basal function in Huntington’s disease model with detectable changes with a PDE10A PET radioligand [140••]." (PMID 30291526, 2018). "In other striatal disorders, such as Parkinson's and Huntington's disease, similarly lower availability of striatal PDE10A has been reported before any volumetric signs of degeneration are obvious." (PMID 28267149, 2017). "In PET studies with [11C]52 in patients with Huntington’s disease, an altered PDE10A expression was detectable early before symptomatic onset." (PMID 27213312, 2016). "Our results further attest to the sensitivity of small‐animal PET studies in measuring changes in PDE10A levels in preclinical models of disease such as has recently been shown in a Huntington's disease mouse model." (PMID 27247380, 2016). "The present results strongly support the investigation of PDE10A inhibitors as a much needed new treatment approach to Huntington's disease." (PMID 20976216, 2010). "More significantly, our studies point directly to an accessible new therapeutic approach to slow Huntington's disease progression, namely, PDE10A inhibition." (PMID 20976216, 2010). "The degeneration of striatal MSNs is a cardinal pathology in Huntington’s disease and there are several lines of preclinical evidence suggesting that PDE10A inhibition may ameliorate this degenerative process." (PMID 39056811, 2024). "PDE10A inhibitors have also been studied for the treatment of Huntington’s disease." (PMID 39056811, 2024). "At present, we are unaware of ongoing trials of PDE10A inhibitors for Huntington’s disease." (PMID 39056811, 2024).
Huntington disease (continued). "PDE10A coordinates cAMP signaling in striatal medium spiny neurons, the main input region of the basal ganglia circuitry and the most vulnerable cells to degeneration during Huntington’s disease (HD)." (PMID 31871190, 2020). "Moreover, several pre-clinical studies have shown that PDE10A inhibitors can protect striatal MSNs against neurodegeneration in Huntington’s disease (HD) models through the improvement of cAMP signaling." (PMID 25815469, 2015). "It will be of considerable interest to investigate whether similar beneficial effects of PDE10A inhibition are observed in other preclinical models of Huntington's disease using a broader range of analytical techniques." (PMID 20976216, 2010). "In addition, the inhibition of PDE10A (the striatal-specific PDE) in a mouse model of Huntington’s disease resulted in significant amelioration in striatal cell survival, elevated levels of BDNF and phosphorylated CREB, as well as improvement in rotarod performance." (PMID 28753652, 2017).
Parkinson disease (17 papers, 2012 to 2026). A progressive degenerative disorder of the central nervous system characterized by loss of dopamine producing neurons in the substantia nigra and the presence of Lewy bodies in the substantia nigra and locus coeruleus. "The PDE10A/cAMP interaction is essential for dopamine neurotransmission, and has been implicated in the pathophysiology of Parkinson’s disease." (PMID 33668128, 2021). "Investigators have reported that alteration of PDE10A expression is associated with progression and severity of patients with parkinsonism." (PMID 33668128, 2021). "This radioligand has also been used to demonstrate striatal and pallidal loss of PDE10A expression, which is associated with duration and severity of motor symptoms and complications in Parkinson’s disease." (PMID 27213312, 2016). "In this regard, recent work has demonstrated that striatal reduction of PDE10A levels is associated with the duration and severity of Parkinson disease." (PMID 27058447, 2016). "The indication that PDEs are intimately involved in the pathophysiology of different movement disorders further stems from recent discoveries that mutations in genes encoding different PDEs, including PDE2A, PDE8B, and PDE10A, are responsible for rare forms of monogenic parkinsonism and chorea." (PMID 34155691, 2021). "Tremendous effort has been dedicated to developing PDE10A inhibitors for the treatment of Parkinson’s disease and other neuropsychiatric disorders characterized by regulating medial striatal neuron (MSN) activity." (PMID 33668128, 2021). "Furthermore, it will be important to establish whether the observation of parkinsonism with nigrostriatal degeneration in individual 3 is coincidental or whether individuals with de novo PDE10A mutations are also at an increased risk of developing degeneration of nigral neurons." (PMID 27058447, 2016). "In a rat model of Parkinson's disease, it was shown that ventral striatal PDE10A expression and activity increase with concomitantly decreased dorsal striatal expression and activity." (PMID 27247380, 2016). "Given its high and selective presence in striatal MSNs, PDE10A is a primary target in pharmacological research for diseases where dysregulation of striatal circuits is believed to be crucial (e.g., psychosis, Huntington disease, substance abuse, and Parkinson disease)." (PMID 27058447, 2016). "Given the importance of striatal dopamine signaling for disorders such as schizophrenia, Parkinson’s disease, L-DOPA-induced dyskinesia and others, PDEs (including PDE10A) have been investigated as potential targets for pharmaceutical interventions in these disorders." (PMID 35883657, 2022).
Obesity (11 papers, 2011 to 2025). Accumulation of substantial excess body fat. "Interestingly, studies in mice implicated PDE10A in thermoregulation and obesity: inhibition of phosphodiesterase 10A appeared to stimulate thermogenic gene expression and reduce hedonic feeding." (PMID 40229704, 2025). "The PDE10A encodes for a phosphodiesterase implicated in the regulation of energy homeostasis and it has been proposed as a promising candidate target for the treatment of obesity and diabetes." (PMID 29522525, 2018). "As with PDE3B, this may also be due to increased inflammatory signaling associated with obesity as the PDE10A promotor harbors a binding site for the pro‐inflammatory transcription factor NF‐kappaB in mice and humans." (PMID 27247380, 2016). "Furthermore, in vivo quantification of PDE10A in pre-clinical PET studies revealed an increase in the availability of this enzyme in both the striatum and the brown adipose tissue in obese mice pointing to an association of PDE10A with obesity." (PMID 27213312, 2016). "PDE10A knockout mice exhibit a resistance to diet-induced obesity and multiple behaviour abnormalities, e.g., decrease in exploratory locomotor activity." (PMID 37072725, 2023). "In DIO and ob/ob mice, the [18F]34 uptake was significantly increased by about 80% in the BAT and 25–75% in the striatum compared to NW mice indicating a noticeably elevated PDE10A availability in obesity." (PMID 33917199, 2021). "It is also worth noting that pharmacological inhibition of PDE10A protects mice against diet-induced obesity and insulin resistance, thus presenting the potential benefits of treatment with PDE10A inhibitors." (PMID 33153226, 2020). "Collectively, our findings highlight a novel thermoregulatory role for PDE10A in mouse and human adipocytes and promote PDE10A inhibitors as promising candidates for the treatment of obesity and diabetes." (PMID 27247380, 2016). "We have characterized an entirely novel role for PDE10A in adipose tissue and, for the first time, have translated the anti‐obesity potential of phosphodiesterase inhibitors from preclinical models to humans." (PMID 27247380, 2016). "Recently, PDE10A-selective inhibitors have also been suggested to be useful in the treatment of diabetes and obesity." (PMID 21494592, 2011). "More significantly, PDE10A genetic knock-out or pharmacological inhibition reduces the adverse metabolic consequences of high-fat diets in mouse models of metabolic syndrome and obesity." (PMID 39056811, 2024). "Therefore, PDE10A inhibitors are ideally placed for the treatment of obesity due to their dual ability to suppress hedonic feeding and increase energy expenditure." (PMID 27247380, 2016). "Based on these preliminary results we hypothize that PDE10A might be a novel therapeutic target for treatment of obesity." (PMID 27213312, 2016). "It is noteworthy that changes in PDE10A expression may differ within sub‐regions of the striatum in obesity." (PMID 27247380, 2016). "Hence, we used [18F]47 in PET/MR studies in various mouse models of obesity with the aim to quantify PDE10A not only in striatum but also in brown adipose tissue (BAT)." (PMID 27213312, 2016). "The preliminary results clearly point to a relationship between PDE10A activity and the regulation of energy homeostasis including thermogenic gene expression, lipolysis and glucose uptake suggesting that PDE10A might be a suitable target for the treatment of obesity." (PMID 33917199, 2021). "In addition, our results further provide evidence that pharmacological inhibition of PDE10A might be a promising strategy for the treatment of obesity and diabetes." (PMID 33917199, 2021). "Notably, although there is evidence that PDE10A is involved in the regulation of whole body energy balance, to the best of our knowledge, PDE10A expression associated with obesity has not been analyzed so far." (PMID 27213312, 2016).
Obesity (continued). "Furthermore, in a study investigating diet-induced obesity, researchers found that inhibition of PDE10A, either through genetic deletion or pharmacological blockade, substantially increased weight loss and insulin sensitivity, while reducing adiposity in mice fed on a Western-style diet." (PMID 25297556, 2014). "Together, these data suggest that PDE10A expression increases in interscapular BAT and striatum in various models of obesity in mice." (PMID 27247380, 2016).
colorectal cancer (10 papers, 2016 to 2025). A primary or metastatic malignant neoplasm that affects the colon or rectum. "Elevated PDE10A expression has been documented in multiple cancer types, including colorectal cancer (CRC) and non-small cell lung cancer (NSCLC)." (PMID 41179677, 2025). "We focused only on the combinations involving the PDE10A inhibitor PF-2545920 because there is evidence of the high accumulation of this drug in the brain, and it was shown to be effective in colorectal cancer." (PMID 34575827, 2021). "A biological role for PDE10A has also been studied in neurodegenerative diseases and in colorectal cancer." (PMID 33450964, 2021). "The findings that PDE10A is induced in human colon tumor cells and that MP‐10 halts tumor cell growth through PKG signaling and induces apoptosis, further add that PDE10A inhibitors may have multiple applications in obese patients with comorbid colorectal cancer." (PMID 27247380, 2016).
lung carcinoma (10 papers, 2017 to 2023). "Activated cGMP/PKG signaling through PDE10A inhibition was shown to decrease β-catenin signaling in colon and lung cancers." (PMID 36324187, 2022). "Again, our results mirror those seen in colon and lung cancer cells in which PDE10A inhibition arrested the cell cycle, induced apoptosis, and inhibited cancer growth." (PMID 36324187, 2022). "PDE10A inhibition in lung cancer was shown to decrease MAPK signaling." (PMID 36324187, 2022). "PDE10A expression correlates with lung cancer prognosis, and its pharmacological inhibition suppresses growth of NSCLC cell lines 15, so it seems a plausible candidate gene for lung cancer risk." (PMID 29766673, 2018). "Panel b displays lung cancer SL pairs GUCY1A2-TYMS and PDE10A-TYMS, treated with leucovorin and capecitabine." (PMID 37737478, 2023). "Inhibition of PDE10A by either genetic silencing or pharmacological inhibition was also reported to decrease cancer cell growth through increased cGMP/PKG signaling and subsequent decreased β-catenin-dependent TCF/LEF transcriptional activity in colon and lung cancer cells." (PMID 36324187, 2022).
psychosis (9 papers, 2011 to 2024). "PDE10A has been implicated in the pathophysiology of psychosis." (PMID 22205951, 2011). "Nonetheless, there remain significant gaps, notably on the effects of PDE10A inhibitors in humans, both healthy and suffering psychosis." (PMID 33551724, 2020). "Recently, there has been an industry-wide effort to develop and test inhibitors of phosphodiesterase 10A (PDE10A) as a novel mechanism to ameliorate psychosis." (PMID 33551724, 2020). "Given the notable similarities in the effects of PDE10A inhibitors and D2 receptor antagonists across a range of experimental paradigms, why are only the latter compounds efficacious for ameliorating psychosis and delusions?" (PMID 33551724, 2020). "However, whether PDE10A availability is primary or secondary to cortical thinning requires further study in the early stages of the psychotic disorder or, preferably, in a longitudinal investigation." (PMID 28267149, 2017). "Bipolar disorder with psychosis and/or substance abuse in the absence of alcohol dependence was associated with the rare variant rs1039002 in the vicinity of the gene phosphodiesterase 10A (PDE10A) on chromosome 6q27 (p = 1.7×10−8)." (PMID 22205951, 2011). "These outcomes indicate that modulation of the mGluR2 results in effective restoration of abnormalities in AEP components in two widely used animal models of psychosis, whereas PDE10A inhibition does not." (PMID 26808689, 2016).